ATG5 (autophagy related 5)
Diseases named in the same sentence as ATG5 in open-access papers (continued):
Sharing a sentence is not in itself a finding about the gene and the disease.
esophageal cancer (8 papers, 2016 to 2022). A primary or metastatic malignant neoplasm involving the esophagus. "Consistent with this study, a recently published paper reported that down-regulating ATG5 could enhance 5-FU-induced autophagy-associated and apoptosis-independent cell death in esophageal cancer cells." (PMID 29382381, 2018). "The results showed that esophageal cancer patients with lower expression of ATG5 had a longer overall survival." (PMID 32974198, 2020). "In order to investigate the role of autophagy response induced by CPT in the growth of ESCC cells, we blocked autophagy pathway via siRNA silencing of autophagy essential genes Beclin1 or ATG5 and evaluated its effect on proliferation and apoptosis of esophageal cancer cells." (PMID 33898327, 2021). "The statistically higher expressions of PLAUR, BIK, DRAM2, RNF41, STK38, ATG5, and PARP1 were measured in esophageal cancer than those in normal tissue, while statistically significant differences were also detected between ESCC and esophageal adenocarcinoma (EAC)." (PMID 32974198, 2020).
type 2 diabetes (8 papers, 2018 to 2025). "According to our research, obese type 2 diabetic (T2D) rats have been found to have adipose tissue-activated autophagy, which is characterized by increased expression of the autophagy genes Atg5, LC3-II, and Beclin -1 and decreased expression of mTOR." (PMID 38698047, 2024). "Clinical studies have shown that ATG5 expression was decreased in skeletal muscle from type 2 diabetes." (PMID 35992146, 2022). "A study analyzing gene expression between individuals with type II diabetes and controls found differential expression of the RIG‐I‐like receptor signaling pathway, highlighting the genes TBK1, ATG5, TANK, IL8, and MAVS." (PMID 40476695, 2025). "In an animal study, the expression of Atg-5 and conversion of LC3-II to LC3-I were significantly enhanced by liraglutide, indicating that liraglutide enhanced autophagy in a high-fat diet and streptomycin-induced type 2 diabetic mice." (PMID 31336911, 2019). "Activated autophagy characterized by an increased expression of autophagy genes ATG5, LC3A, and LC3B as well as elevated autophagic flux in omental and subcutaneous adipose tissue has been reported in non-diabetic obese individuals more pronounced as in type 2 diabetes (T2D) patients." (PMID 29507613, 2018).
acute kidney injury (7 papers, 2018 to 2024). Sudden and sustained deterioration of the kidney function characterized by decreased glomerular filtration rate, increased serum creatinine or oliguria. "In acute kidney injury, ATG5-dependent autophagy alleviates renal damage by inhibiting the activation of p65." (PMID 39224841, 2024). "Elabela has been reported to rescue acute kidney injury in mice by reducing the levels of autophagy factors such as ATG5 and LC3B II." (PMID 36611895, 2022). "Genetically modified mice with tamoxifen-induced inhibition of Atg5 in the proximal tubules demonstrated renal failure, the atrophy of kidney tissue, mitochondrial dysfunction, and an increase in oxidative stress products in the kidney." (PMID 30360430, 2018). "In this study, we utilized mice with conditional deletion of the Atg5 gene in proximal tubules and monitored the long-term dynamic regulation of autophagy following ischemic acute kidney injury (AKI)." (PMID 39639205, 2024). "In terms of autophagy, conditional proximal tubule-specific KO mice for Atg5 or Atg7 display enhanced renal injury compared to wild-type mice in response to induced acute kidney injury (AKI) or chronic kidney disease (CKD)." (PMID 35805186, 2022). "Selective tubular cell Atg5 and Atg7 knockout mice develop more severe tubular cells damages and acute kidney injury (AKI) after ischemia-reperfusion injury." (PMID 30654583, 2019).
fibrosis (7 papers, 2020 to 2024). the formation of excess fibrous connective tissue in an organ or tissue in a reparative or reactive process. "The results indicated that ATG5 knockdown by rAAV9-shRNA-ATG5 in mice for 7 weeks alleviated DOX-induced cardiac dysfunction, cardiac fibrosis, oxidative stress, and myocardial apoptosis, and ATG5 overexpression by rAAV9-ATG5 exerted the opposite effects." (PMID 39931517, 2024). "A role of miR-30a in suppressing airway fibrosis and autophagy by targeting ATG5 (autophagy-related gene 5) has been shown." (PMID 35455659, 2022). "However, Atg5 knockdown in mice showed that impairment of autophagy aggravated CS-induced pulmonary inflammation and fibrosis." (PMID 31947943, 2020). "In the context of lung epithelial cells, it impedes autophagy by targeting CTGF and ATG5, effectively hampering the EMT process, a crucial step in silicotic fibrosis inhibition." (PMID 39551792, 2024).
Hepatic steatosis (7 papers, 2015 to 2025). Steatosis is a term used to denote lipid accumulation within hepatocytes. "Liver-specific Vps34 knockout mice developed hepatomegaly and hepatic steatosis, which is highly similar to the phenotype observed in the autophagy-deficient Atg7−/− and Atg5−/− livers." (PMID 26589724, 2015). "Nevertheless, pharmaceutical enhancement of autophagy by rapamycin or carbamazepine which inhibits mTOR reduced hepatic steatosis in NASH model, and severe hepatic steatosis occurs in mice with hepatic deletion of Atg5." (PMID 36009582, 2022). "Herein, MG increased ATG5-12, ATG7, Beclin1, ULK1, and LC3-II/I ratio and decreased p62/SQSTM1 and p-mTOR in the liver of Tylo-injected rats and PA-stimulated HepG2 cells, suggesting that MG might promote the formation of autophagic flux to alleviate hepatic steatosis." (PMID 32992548, 2020).
myocardial infarction (7 papers, 2018 to 2023). Gross necrosis of the myocardium, as a result of interruption of the blood supply to the area, as in coronary thrombosis. "Thereafter, the SVM-RFE algorithm, random forest algorithm, and LASSO algorithm were utilized to identify mitophagy genes associated with myocardial infarction, including ATG5, TOMM20, and MFN2." (PMID 37304955, 2023). "In mice, inhibition of autophagy by bafilomycin, or genetic beclin heterozygosity as well as ATG5 knockout impairs angiogenesis post myocardial infarction, whereas the angiogenic factor AGGF1 enhances therapeutic angiogenesis through JNK-mediated stimulation of endothelial autophagy." (PMID 31580256, 2019). "In myocardial cells after myocardial infarction (MI), miR-30d inhibited autophagy by binding to ATG5 and subsequently enhanced ferroptosis." (PMID 33424539, 2020). "In mice subjected to diabetic cardiomyopathy or myocardial infarction (MI) induced-surgery, Melatonin promoted heart function by enhancing autophagy and weakening apoptosis, as indicated by the elevated expression levels of Beclin1, Atg5, LC3II, and decreased p62." (PMID 29577047, 2018). "Transfection with ad‐LAMP2 mitigated the area of myocardial infarction from 57% to 31%, and co‐transfection with Ad‐LAMP2 and Ad‐ATG5 gained more protection to approximately 21%." (PMID 36562207, 2023).
renal cell carcinoma (7 papers, 2014 to 2022). "Moreover, the LC3B/ATG5-dependent autophagy was shown to be required for the development of VHL-deficient renal cell carcinomas in nude mice." (PMID 24763318, 2014). "miR-30d-5p also functioned to impede cell activity through the downstream factor ATG5 in renal cell carcinoma." (PMID 35155437, 2022). "In renal cell carcinoma cells, ATG5 silencing or 3-MA treatment in combination with Sorafenib enhanced the sensitivity of RCC cells to Sorafenib." (PMID 33718194, 2021). "Moreover, miR-30d-5p overexpression reduced the level of ATG5, thus obviously inhibited the proliferation of tumor cells in renal cell carcinoma, and slowed the transition from the G1 to the S phase of the cell cycle." (PMID 35155437, 2022). "The mechanism of ROC-325 is to antagonize renal cell carcinoma (RCC) growth and survival by inhibiting ATG5/7-dependent autophagic degradation and inducing apoptosis." (PMID 36034776, 2022). "In Renal cell carcinoma RCC, ROC-325 induced an accumulation of autophagosomes in vitro and inhibited RCC growth and survival in an ATG5/7-dependent manner in vivo by disrupting autophagic degradation." (PMID 33718194, 2021). "For instance, AIM2 was capable of inhibiting the proliferation, invasion and migration of renal cell carcinoma (RCC) cells by upregulating autophagy-related genes (Bcl-2, Beclin-1, LC3-II and ATG5)." (PMID 31492049, 2019).
tuberculosis (7 papers, 2012 to 2025). A chronic, recurrent infection caused by the bacterium Mycobacterium tuberculosis. "A recent study, however, has shown that many autophagy-gene-deficient mice are resistant aerosol-induced tuberculosis, whereas atg5-deficient mice show a neutrophil-dependent increased susceptibility to tuberculosis." (PMID 29118429, 2017). "ATG5 rs2245214 polymorphism has been previously studied in patients with tuberculosis and lupus erythematous." (PMID 26030385, 2015). "Polymorphism ATG5 rs2245214 has been previously studied in patients with head and neck squamous cell carcinoma, non-medullary thyroid cancer, Paget disease of bone, tuberculosis and lupus erythematous with heterogeneous results." (PMID 35123435, 2022). "ATG5 is one of the core autophagy proteins with additional functions such as noncanonical membrane atg8ylation, which among a growing number of biological outputs includes control of tuberculosis in animal models." (PMID 39026874, 2024). "Therefore, our new findings and future dissection of the ATG5-dependent mechanisms of regulating neutrophil recruitment to the lungs during M. tuberculosis infection will provide critical insight into how to promote protective immune responses to TB." (PMID 37319285, 2023).
bladder cancer (6 papers, 2019 to 2024). "In our study, the autophagy process induced by C-2 is associated with autophagy factors such as ATG7, ATG5, ATG3, p62, LC3 and Beclin-1, therefore, the ability of C-2 to induce autophagy in bladder cancer cell lines was confirmed." (PMID 31685029, 2019). "Single nucleotide polymorphisms associated with bladder cancer progression and recurrence, in the autophagy genes ATG2B (rs3759601) and ATG5 (rs2245214), affected both the in vitro and in vivo training effect of BCG." (PMID 31447834, 2019). "ATG5 and ATG7 knockout mouse models would also help to understand the possible role of SCFA on autophagy, as for example, butyrate induced mTOR pathway-activated autophagy in bladder cancer cells and nasopharyngeal carcinoma cells." (PMID 32664466, 2020).
chronic myeloid leukemia (6 papers, 2020 to 2024). "In addition to ATG5, Bcl-2 is a direct target of miR-153-3p in combating resistance to Imatinib in chronic myeloid leukemia." (PMID 35211417, 2022). "It has been reported that Atg5 is the target of miR-30a in chronic myeloid leukemia cells." (PMID 32251287, 2020). "In contrast, in chronic myelocytic leukemia (CML), LINC00470 has been shown to bind METTL3 and positively regulate the m6A modification levels of PTEN mRNA, consequently downregulating ATG5 expression and leading to chemotherapy resistance." (PMID 39468015, 2024). "Moreover, blocking autophagy using pharmacological blockers (CQN), or silencing of ATG5 and ATG7, significantly enhanced the killing of imatinib-resistant cells in chronic myelogenous leukemia." (PMID 37761021, 2023). "Several autophagy-related genes (Beclin-1, Agt4, and Atg5) are upregulated, and the silencing of these genes negatively affects cell survival; as a result, the extent of autophagy in chronic myeloid leukemia (CML) appears to be related to the status of CSCs in the tumor." (PMID 32391363, 2020). "However, researchers suggested a Beclin1 autophagy-dependent but ATG5 autophagy-independent role in murine chronic myeloid leukemia (CML) model, whereas Beclin1 knockdown, but not Atg5 ablation, leads to a reduced leukemic burden and a significantly higher survival rate of targeted mice." (PMID 37180758, 2023).
Left ventricular dilatation (6 papers, 2013 to 2022). Enlargement of the chamber of the left heart ventricle. "Conversely, mice with cardiac‐specific deficiency of Atg5 develop left ventricular dilatation and contractile dysfunction." (PMID 35845350, 2022). "In vivo evidence demonstrates that cardiac‐specific Atg5‐deficient mice develop cardiac dysfunction and left ventricular dilatation 1 week after transverse aortic constriction." (PMID 28181410, 2017). "Moreover, in adult mice, temporally controlled cardiac‐specific deficiency of Atg5 led to various cardiomyopathies including cardiac hypertrophy, left ventricular dilatation, and contractile dysfunction." (PMID 35845350, 2022). "For example, cardiac-specific loss of ATG5 resulted in LVH, left ventricular dilatation and contractile dysfunction in mice." (PMID 23894332, 2013). "For instance, three different cardiomyocyte-specific ATG5 conditional knockout (KO) mouse models display left ventricular dilatation and cardiac dysfunction without or with pressure overload." (PMID 36312227, 2022).
lymph node metastasis (6 papers, 2014 to 2024). "Beclin-1 expression was associated with lymph node metastasis and tumor grade, whereas Atg5 expression was associated with tumor grade, clinical stage, tumor size, and lymph node metastasis." (PMID 39650649, 2024). "ATG5 expression was positively associated with large tumor size, lymph node metastasis, and EGFR expression." (PMID 37735252, 2023). "ATG5 expression was found associated with tumor grade, tumor size, clinical stage and lymph node metastasis and clinical outcome in OSCC." (PMID 29207660, 2017).
rheumatoid arthritis (6 papers, 2017 to 2022). A chronic, systemic autoimmune disorder characterized by inflammation in the synovial membranes and articular surfaces. "Investigators have reported upregulation of ATG5 protein in T cell-infiltrated inflammatory areas of patients with rheumatoid arthritis, and ATG5 variants are associated with neuromyelitis optica in southern Chinese Han population." (PMID 35518570, 2022).
Ureteral obstruction (6 papers, 2018 to 2025). Obstruction of the flow of urine through the ureter. "Using a myeloid cell-specific Atg5 knockout (MΦ atg5−/−) mouse, we established renal ischemia/reperfusion and unilateral ureteral obstruction models to evaluate the role of macrophage Atg5 in renal macrophage migration and fibrosis." (PMID 38594728, 2024). "In the unilateral ureteric obstruction model, the deletion of tubular epithelial ATG5 genes significantly inhibited autophagy, which led to heightened nuclear factor κB (NF-κB) activation, increased proinflammatory cytokines in the obstructed kidneys." (PMID 38099142, 2023). "Therefore, this study aimed to investigate the function of Atg5 using mouse models of ischemia/reperfusion (I/R) injury and unilateral ureteral obstruction (UUO)." (PMID 38594728, 2024).
childhood asthma (5 papers, 2012 to 2023). "However, the ATG5 rs510432 SNP has been shown to influence other diseases of the immune system associated with childhood asthma and epilepsy associated with overdominant action on phenotypes." (PMID 38136993, 2023). "Rs510432 could increase promotor activity of ATG5 and was associated with childhood asthma." (PMID 34661876, 2022). "In previous studies, mir-335-5p has been found to inhibit the inflammatory response in chronic rhinosinusitis; and moreover mir-335-5p could alleviate the inflammatory response and airway fibrosis by modulating ATG5, resulting in relief of childhood asthma." (PMID 36118873, 2022).
developmental delay (5 papers, 2016 to 2026). "For instance, mutations in ATG5 are linked to congenital ataxia and developmental delay, while WIPI2 mutations result in global developmental delay and intellectual disability, demonstrating the diverse roles of autophagy proteins in neuronal health." (PMID 41277110, 2026). "A homozygous missense mutation in ATG5 found in two siblings resulted in congenital ataxia, mental retardation and developmental delay." (PMID 41277110, 2026). "Mutations in the ATG5 gene are related with congenital childhood ataxia with mental retardation, and developmental delay." (PMID 33917666, 2021). "We identified a homozygous missense mutation, changing a conserved amino acid, in ATG5 in two siblings with congenital ataxia, mental retardation, and developmental delay." (PMID 26812546, 2016).
gallbladder cancer (5 papers, 2014 to 2024). "However, the interaction of the long non-coding RNA (lncRNA) gallbladder cancer drug resistance-associated lncRNA1 with phosphoglycerate kinase 1 in gallbladder cancer cells prevents ATG5 degradation and induces the ATG5-ATG12 complex formation, promoting autophagy and doxorubicin resistance." (PMID 39850800, 2024).
head and neck squamous cell carcinoma (5 papers, 2014 to 2025). A squamous cell carcinoma that arises from any of the following anatomic sites: lip and oral cavity, nasal cavity, paranasal sinuses, pharynx, larynx, and salivary glands. "Studies indicate that inhibiting autophagy-related proteins, specifically SLC7A5/LAT1 and ATG5, increases radiosensitivity in head and neck squamous cell carcinomas (HNSCC)." (PMID 39655194, 2024). "MiR-630 was also found to be upregulated in head and neck squamous cell carcinoma after cisplatin treatment and can modulate the protein expression of ATG5, ATG6/BECN1, ATG10, ATG12, ATG16L1 and UVRAG." (PMID 24621930, 2014).
Hyperglycemia (5 papers, 2016 to 2025). An increased concentration of glucose in the blood. "Hyperglycemia reduces LC3-II and ATG5 protein levels which contribute to deficiencies in the autophagy process, with development and progression of DN." (PMID 36313818, 2022). "Moreover, there was an increase in the expression levels of ATG12–ATG5 complex, ATG5, and ATG3 and the conversion of LC3B-I to LC3B-II under hyperglycemia in a retinal Müller cell line." (PMID 40735446, 2025). "However, the anti-IL-23 treatment prevented hyperglycemia in Atg5 CD11cKO mice (p < 0.05) while not affecting fasting blood glucose levels in WT mice." (PMID 35301333, 2022).
Hypertension (5 papers, 2013 to 2023). The presence of chronic increased pressure in the systemic arterial system. "Mitophagy acts as a protective mechanism during hypertension and enhanced ATG-5-mediated mitophagy during Ang II-induced hypertension results in reduced levels of ROS and inflammation." (PMID 38020895, 2023). "Additionally, our data demonstrated that a maternal high-fructose diet combined with a post-weaning high-fat diet, but not high-fat diet reduced Ulk1, Atg5, and Nrf2 mRNA levels, induced a greater degree of oxidative stress and hypertension." (PMID 29315230, 2018). "We measured Atg5 and LC3A/B to determine whether hypertension modulated autophagy in the kidney." (PMID 24159376, 2013).
inflammatory bowel disease (5 papers, 2021 to 2025). A spectrum of small and large bowel inflammatory diseases of unknown etiology. "The interaction of autophagy proteins, which also include BECN1, L-chain microtubule-associated protein 3 (LC3/LC3-II) and autophagy-related (ATG) protein 5 (ATG5) with inflammatory bowel disease (IBD) susceptibility genes is discussed." (PMID 36835075, 2023). "Controlling the switch between the pro-autophagic and pro-apoptotic functions of Beclin 1 and autophagy-related 5 (ATG5) by cytosolic HMGB1 during inflammation has also been reported in inflammatory bowel disease." (PMID 35954253, 2022). "Activated Atg3- and Atg5-deficient T cells differentiated in vitro into TH9 cells show increased production of IL-9 compared to their WT counterparts, and mutations in core autophagy genes increase the risk for development of inflammatory bowel disease (IBD) in humans." (PMID 37708826, 2023).